YTHDC2 (YTH N6-methyladenosine RNA binding protein C2)
Description:
3'-5' RNA helicase that plays a key role in the male and female germline by promoting transition from mitotic to meiotic divisions in stem cells. Specifically recognizes and binds N6-methyladenosine (m6A)-containing RNAs, a modification present at internal sites of mRNAs and some non-coding RNAs that plays a role in the efficiency of RNA processing and stability. Essential for ensuring a successful progression of the meiotic program in the germline by regulating the level of m6A-containing RNAs (By similarity). Acts by binding and promoting degradation of m6A-containing mRNAs: the 3'-5' RNA helicase activity is required for this process and RNA degradation may be mediated by XRN1 exoribonuclease. Required for both spermatogenesis and oogenesis (By similarity).
Synonyms: hYTHDC2; FLJ2194; FLJ10053; DKFZp564A186; CAHL
Tractability: Small molecule: it has a binding pocket of medium quality. PROTAC: ubiquitination databases record sites on it; its protein half-life has been measured.
Gene: Protein-coding gene on chromosome 5 (113,513,694 to 113,595,287, forward strand). Ensembl gene ENSG00000047188.
Subcellular location: Cytoplasm; Cytoplasm, perinuclear region
Subcellular location (Human Protein Atlas): Nucleoplasm; Cytoplasmic bodies; Nuclear bodies
Pathways (Reactome):
Metabolism of RNA: Nuclear RNA decay
Gene Ontology:
Molecular function: 3'-5' RNA helicase activity; ATP hydrolysis activity; ATP-dependent activity, acting on RNA; N6-methyladenosine-containing RNA reader activity; protein binding; RNA binding; RNA polymerase binding; helicase activity; ATP binding; nucleic acid binding; RNA helicase activity
Biological process: host-mediated activation of viral genome replication; response to interleukin-1; response to tumor necrosis factor; germline cell cycle switching, mitotic to meiotic cell cycle; oocyte development; spermatid development
Cellular component: endoplasmic reticulum; cytoplasm; nucleoplasm; ribonucleoprotein granule; perinuclear region of cytoplasm
Genetic constraint (gnomAD): Loss-of-function variants: 37 observed, 148.93 expected, observed/expected ratio (o/e) 0.25, 90% interval 0.19 to 0.33. The upper end of that interval is the gene's LOEUF score, 0.33, which puts it in group 1 of 6, group 1 being the genes least tolerant of losing a copy. Missense variants: 1,536 observed, 1,640.4 expected, observed/expected ratio (o/e) 0.94, 90% interval 0.9 to 0.98. Synonymous variants: 624 observed, 554.55 expected, observed/expected ratio (o/e) 1.13, 90% interval 1.05 to 1.2.
Homologues: Orthologues: chimpanzee YTHDC2 (99% identical), macaque YTHDC2 (99% identical), pig YTHDC2 (97% identical), rat Ythdc2 (97% identical), mouse Ythdc2 (97% identical), guinea pig YTHDC2 (97% identical), rabbit YTHDC2 (93% identical), tropical clawed frog ythdc2 (81% identical), zebrafish ythdc2 (62% identical), Drosophila melanogaster CG8915 (22% identical). Paralogues in human: DHX57 (25% identical), DHX9 (24% identical), DHX36 (23% identical), DHX29 (23% identical), DHX30 (20% identical), DHX34 (18% identical), TDRD9 (18% identical), DHX38 (16% identical), DHX16 (16% identical), DHX15 (16% identical), DHX37 (16% identical), DHX8 (15% identical), and 6 more.
Diseases named in the same sentence as YTHDC2 in open-access papers:
YTHDC2 is named in the same sentence as 113 diseases in open-access papers, as found by Europe PMC text mining. Sharing a sentence is not in itself a finding about the gene and the disease. The quoted sentences say what the papers report.
colon cancer (23 papers, 2018 to 2025). "Studies have also shown that YTHDC2 can promote colon cancer metastasis through HIF-1 and is a potential diagnostic and therapeutic target of this tumor." (PMID 35155557, 2022). "YTHDC2 may promote the metastasis of colon cancer by promoting the translation of HIF-1α, and YTHDC2 may be a diagnostic marker and target gene for the treatment of colon cancer." (PMID 34124065, 2021). "Another study found that YTHDC2 was highly expressed in human colon cancer tissues; a significantly positive correlation was detected between YTHDC2 expression and colon cancer stage, suggesting that YTHDC2 was potentially a diagnostic marker and target gene for treating colon cancer." (PMID 34721530, 2021). "Another study found that YTHDC2 acts as a promoter in colon cancer metastasis and may be a diagnostic marker for colon cancer patients." (PMID 32552682, 2020). "YTHDC2 upregulates in colon cancer and has an obviously positive correlation with tumor stage, indicating YTHDC2 may be a diagnostic marker for colon cancer patients." (PMID 30062093, 2018). "YTHDC2 can promote the translation of target mRNAs, and it may serve as an activator in colon cancer metastasis and could be a diagnostic marker for individuals with colon cancer." (PMID 37928762, 2023). "The findings indicate a significant positive correlation between YTHDC2 expression levels and tumor stage in colon cancer patients, underscoring the pivotal role of YTHDC2 in cancer progression." (PMID 40136363, 2025). "One study found a positive correlation between YTHDC2 and the clinical stage of colon cancer, including metastasis." (PMID 35155557, 2022). "The knockdown of YTHDC2 in colon cancer cells reduces the expression of metastasis-related proteins such as HIF-1α and inhibits tumor metastasis." (PMID 35155557, 2022). "YTHDC2 has been reported to contribute to colon cancer metastasis by promoting the translation of HIF-1α and its related pathways." (PMID 34326699, 2021). "The expression of YTHDC2 was found to be positively correlated with the colon tumor stage, including metastasis." (PMID 33456561, 2021). "YTHDC2 has been recognized to be associated with the development of certain types of cancer, including HCC 27 and colon cancer." (PMID 34326699, 2021). "Previously, in colon cancer, it has been found a significantly positive correlation between YTHDC2 expression and the tumor stage 59." (PMID 32398949, 2020). "YTHDC2 also plays an important role in the metastasis of colon cancer." (PMID 35155557, 2022). "YTHDC2 contributes to colon tumor metastasis by promoting the translation of HIF-1α." (PMID 35155557, 2022). "YTHDC2 results in colon cancer metastasis through augmenting translation of HIF-1α, it may be a potential diagnostic marker and therapy target in colon cancer." (PMID 33015074, 2020). "Recent reports showed that there could be an oncogenic role of YTHDC2 in colon cancer cells and hepatocellular carcinoma cells." (PMID 32258108, 2020). "It has also been proposed that YTHDC2 promotes mRNA translation, based on effects of shRNA knockdown of YTHDC2 in human colon cancer cell lines, as well as measures of apparent translation efficiency of putative YTHDC2 targets in mouse testis and of artificial reporter constructs in HeLa cells." (PMID 29360036, 2018). "RNA helicase YTHDC2 acts as a promoter in colon cancer metastasis by enhancing the translation of hypoxia-inducible factor-1alpha (HIF-1α) gene, which could promote EMT via the transcription factor Twist1." (PMID 30062093, 2018). "Additionally, high levels of YTHDC2 were detected in colon tumors and were positively correlated with tumor stage, indicating that YTHDC2 may act as a diagnostic marker for CRC individuals." (PMID 34381710, 2021). "YTHDC2 can promote cancer metastasis via enhancing the translating efficiency of hypoxia-inducible factor (HIF)-1α in colon tumor cells, and may become a diagnostic marker and target gene for treating colon cancer patients." (PMID 32500031, 2020).
colon cancer (continued). "For instance, upregulated YTHDC2 unwinded the 5′UTR of HIF-1α mRNA and promoted translation initiation, which contributed to colon cancer metastasis." (PMID 33456561, 2021). "Different from IGF2BP2 and IGF2BP3, although the oncogenic roles of YTHDC2 and RBM15 have been identified in colon cancer and acute megakaryoblastic leukemia, their functions in breast cancer await to be identified." (PMID 33585234, 2020).
lung adenocarcinoma (22 papers, 2020 to 2025). A carcinoma that arises from the lung and is characterized by the presence of malignant glandular epithelial cells. "YTHDC2 is down-expressed in lung adenocarcinoma, and is associated with the characteristics of poor differentiation, lymph node metastasis, tumor size and clinical stage of lung adenocarcinoma, and can inhibit the proliferation and migration ability of lung adenocarcinoma cells." (PMID 38028153, 2023). "On the other hand, reduced expression of YTHDC2 correlates with worse clinical outcomes in lung adenocarcinoma (LUAD)." (PMID 40271153, 2025). "Previous studies have shown that YTHDC2 downregulation is a procarcinogenic phenomenon in lung adenocarcinoma (LUAD)." (PMID 39303913, 2024). "For example, both subunits of the Xc−system in the development of lung adenocarcinoma are indispensable for YTHDC2 induced ferroptosis." (PMID 38550378, 2024). "In a recent study, high expression of YTHDC2 was found to induce ferroptosis in lung adenocarcinoma (LUAD) cells." (PMID 38550378, 2024). "In lung adenocarcinoma, one study reported that the YTHDC2 m6A reader binds an SLC7A11 m6A site at the 3′UTR, leading to decreased mRNA stability and expression." (PMID 38023731, 2023). "Additional research has revealed that m6A reader YTHDC2 contributes to ferroptosis in lung adenocarcinoma by targeting SLC3A2." (PMID 36359826, 2022). "Here, we have demonstrated that the m6A reader YT521-B homology domain containing 2 (YTHDC2) is frequently suppressed in lung adenocarcinoma (LUAD)." (PMID 33232910, 2021). "A for the relationship between ferroptosis and m6A modification, the m6A reader YTHDC2 serving as ferroptosis inducer was proved to regulate SLC3A2 in lung adenocarcinoma." (PMID 35127813, 2021). "Recent in vitro studies showed that LDB2 inhibited the proliferation and migration of hepatocarcinoma cells and that LDB2 expression can be upregulated by the m6A reader YTH Domain Containing 2 (YTHDC2) in lung adenocarcinoma to inhibit the proliferation of tumor cells." (PMID 38200081, 2024). "For instance, in lung adenocarcinoma, high HNRNPC and IGF2BP3 levels correlate with reduced overall survival, and a six-gene risk signature (KIAA1429, ALKBH5, METTL3, HNRNPC, YTHDC2, and YTHDF1) strongly correlated with various clinical and pathological features." (PMID 36831575, 2023). "In addition, YTHDC2 could act as an endogenous ferroptosis inducer after targeting SCL3A2 in lung adenocarcinoma." (PMID 38102129, 2023). "For example, YTHDF1 and YTHDC2 act as promoters of ferroptosis in hypopharyngeal squamous cell carcinoma (HPSCC) and lung adenocarcinoma (LUAD)." (PMID 40271153, 2025). "Among these genes, KIAA1429, HNRNPC, YTHDC2, METTL3, WTAP, YTHDC1, and FTO were down expressed in lung adenocarcinoma, RBM15, ZC3H13, YTHDF1, YTHDF2, and ALKBH5 were up expressed." (PMID 32398949, 2020). "YTHDC2, YT521-B homology domain containing 2, is believed to be the final member of the YTH protein family, functioning as a reader to suppress liver steatosis and lung adenocarcinoma." (PMID 36810285, 2023). "METTL3 and YTHDC2 are both ferroptosis inducers that the former could raise cisplatin efficacy in NSCLC and the latter could inhibit lung adenocarcinoma tumorigenesis." (PMID 35090469, 2022). "Moreover, YTHDC2 suppressed SLC3A2 by inhibiting Homeobox A13 (HOXA13) indirectly and was also found to affect system Xc- function in lung adenocarcinoma cells." (PMID 36185243, 2022). "In addition, another study in lung adenocarcinoma (LUAD) demonstrated that METTL3 enhances RNA stability and promotes translation of SLC7A11 through m6A-mediated binding of YTHDF1 and YTHDC2, YTHDC2 prefers to bind to m6A-modified SLC7A11 mRNA and promoting its decay." (PMID 39799112, 2025). "However, their further investigations revealed that inhibition of SLC7A11 by YTHDC2 is not enough to induce ferroptosis in lung adenocarcinoma." (PMID 34926310, 2021).
glioma (12 papers, 2019 to 2024). A benign or malignant brain and spinal cord tumor that arises from glial cells (astrocytes, oligodendrocytes, ependymal cells). "Additionally, YTHDC2 was significantly associated with tumor immune infiltration in skin cutaneous melanoma and brain lower grade glioma." (PMID 37194014, 2023). "YTHDC1 and YTHDC2 are integral components in the molecular landscape of glioma, influencing various aspects of tumor biology." (PMID 38474421, 2024). "In the intricate network of glioma pathogenesis, the YTHDF family, consisting of YTHDF1, YTHDF2, and YTHDF3, and YTHDC1 and YTHDC2, as members of the YTH domain-containing family, play significant roles in the prognosis and molecular mechanisms underlying glioma." (PMID 38474421, 2024). "Subsequently, the differential analysis showed that, between glioma and normal brain tissue, a variety of m6A-related genes were differentially expressed, including METTL14, METTL16, ZC3H13, YTHDC1, YTHDC2, YTHDF2 etc." (PMID 35559019, 2022). "In glioma research, a bioinformatics analysis in the CGGA microarray and RNA sequencing databases showed that the levels of YTHDC2, YTHDF1, YTHDF2, and YTHDF3 were elevated in gliomas." (PMID 34721530, 2021). "There are several independent interaction groups in ‘readers’, suggesting the diverse functions of different ‘readers’, but the expressions of YTHDF2, YTHDC2 and YTHDF1 were significantly correlated with each other in gliomas." (PMID 30810537, 2019). "According to these findings, RP2 may be correlated with m6A modification in glioma, and the combined effect of METTL14, VIRMA, ALKBH5, YTHDC2 and METTL3 may eventually affect the progression and poor prognosis of glioma." (PMID 37602882, 2023). "As is visible in the violin plot, the mRNA expression levels of YTHDF2, YTHDF1, METTL3, RBM15 and HNRNPC were up‐regulated in glioma compared to normal tissues, whereas the expression levels of ALKBH5, WTAP, YTHDC2, ZC3H13 and METTL14, especially of FTO, were decreased in glioma." (PMID 32449290, 2020). "Moreover, YTHDC2 has been identified as an independent negative prognostic indicator for overall survival in gliomas." (PMID 38474421, 2024). "Furthermore, multivariate Cox regression analysis indicated that high expression of YTHDC2 served as an independent positive prognostic factor for overall survival, while elevated expression of IGF2BP3 acted as an independent negative prognostic factor for the overall survival of glioma patients." (PMID 38398118, 2024).
head and neck squamous cell carcinoma (12 papers, 2020 to 2024). A squamous cell carcinoma that arises from any of the following anatomic sites: lip and oral cavity, nasal cavity, paranasal sinuses, pharynx, larynx, and salivary glands. "But based on the research of the TCGA database, YTHDC2 expression is positively associated with the prognosis of head and neck squamous cell carcinoma, indicating that it might also act as a tumor suppressor gene." (PMID 32258108, 2020). "YTHDC2 can act as an independent gene as a prognostic marker of head and neck squamous cell carcinoma (HNSCC)." (PMID 36009239, 2022). "However, a similar study on head and neck squamous cell carcinoma (HNSCC) showed that HNRNPC and YTHDC2 are independent prognostic factors for HNSCC, and the risk score is related to age, gender, stage, and grade." (PMID 34631545, 2021). "YTHDC2 was shown to have the tumor inhibitory effect on head and neck squamous cell carcinoma (HNSCC) and esophageal squamous cell carcinoma (ESCC)." (PMID 34149792, 2021). "In head and neck squamous cell carcinoma, low expression of YTHDC2 is positively correlated with the low levels of B cells, CD8+ T cells, CD4+ T cells, neutrophils, and infiltrating DCs." (PMID 34616742, 2021). "In head and neck squamous cell carcinoma, the low expression of YTHDC2 correlated with lower overall survival (OS), recurrence-free survival, and reduced immune infiltration levels, suggesting its potential as a prognostic and immune infiltration marker for head and neck squamous cell carcinoma." (PMID 38790013, 2024). "Recent studies have found that YTHDC2 is associated with the level of immune infiltration of B cells, CD8+T cells, CD4+T cells, neutrophils and dendritic cells in head and neck squamous cell carcinoma (HNSCC)." (PMID 33777035, 2021). "However, there are few studies on the value of m6A reader protein YTHDC2 in the diagnosis and tumor-infiltrating of head and neck squamous cell carcinoma (HNSCC)." (PMID 33304653, 2020).